FOLR1 (folate receptor alpha)
Diseases named in the same sentence as FOLR1 in open-access papers (continued):
Sharing a sentence is not in itself a finding about the gene and the disease.
ovarian carcinoma (continued). "From 2000 to 2015, there were 13 clinical trials with 148 patients receiving DC immunotherapy for ovarian cancer targeting antigens that included MUC1, MUC16, HER2, and FOLR1, with variable and inconsistently reported results." (PMID 32937961, 2020). "The folate binding protein (FBP), also known as folate receptor-alpha, is a TAA common to both endometrial and ovarian cancer with up to 80-90 fold higher expression in malignant cells compared to normal cells." (PMID 27852036, 2017). "Farletuzumab, is an investigational humanized IgG1-type monoclonal antibody (mAb) targeting folate receptor alpha (FRA), which is expressed on a high percentage of ovarian cancers." (PMID 29016358, 2017). "Ongoing research continues to investigate new promising biomarkers for the early detection of ovarian cancer, such as KLK6/7, GSTT1, PRSS8, FOLR1, and ALDH1." (PMID 26779384, 2015). "Folate receptor alpha (FOLR1/FRA) is expressed in a number of epithelial cancers and in particular epithelial ovarian cancer (EOC), especially of the serous histotype." (PMID 25971554, 2015). "The current study presents data on the utility of a novel marker, folate receptor alpha, FRA; with respect to discrimination between ovarian cancer, for example, the serous histotype, and normal controls." (PMID 23590973, 2013). "Evaluate and compare the utility of serum folate receptor alpha (FRA) and megakaryocyte potentiating factor (MPF) determinations relative to serum CA125, mesothelin (MSLN) and HE4 for the diagnosis of epithelial ovarian cancer (EOC)." (PMID 23590973, 2013). "Prostasin (PRSS8), GSTT1, FOLR1, KLK6, KLK7, and ALDH1 are all currently under research and clinical trials and are also potential biomarkers for early detection of ovarian cancer." (PMID 23319948, 2012). "Promising biomarkers for early detection of ovarian cancer include KLK6/7, GSTT1, PRSS8, FOLR1, ALDH1, and miRNAs." (PMID 23319948, 2012). "In particular, elevated levels of AGR2, GLY, FOLR1, and SMRP in ovarian cancer suggest that simultaneous measurement of these markers may enable early diagnosis." (PMID 41518408, 2026). "In this study, we investigated the role of autophagic cell death triggered by IMGN853 (mirvetuximab soravtansine), an FOLR1-targeted antibody–drug conjugate, and explored potential combinations of IMGN853 with chemotherapeutic drugs used for ovarian cancer treatment." (PMID 40029935, 2025). "After incubation of ovarian cancer cells with scFv-Farletuzumab-SNAP-IR700, high-FOLR1-expressing IGROV1 cells exhibited strong binding and moderate-FOLR1-expressing OVCAR3 cells showed moderate binding, whereas no fluorescence signal was detected in low-FOLR1-expressing cell lines." (PMID 41362788, 2025). "Moreover, the expression patterns of EGFR, Her2, FOLR1, TROP2, and TF in 25 samples of human ovarian cancer tissues was simultaneously visualized using mIF assay." (PMID 41362788, 2025). "Collectively, these results indicate that folate–miR-34a, as expected, inhibited the growth of FOLR1-expressing breast, cervical, and ovarian cancer cells but, unexpectedly, did not exhibit any inhibitory effects on PCa cells." (PMID 38396800, 2024). "Folate receptor 1 (FOLR1), a protein receptor for transporting folate into cells, is expressed at a very low level in normal epithelial cells, but is abnormally upregulated in HCC, ovarian cancer, and pancreatic cancer." (PMID 38057830, 2023). "The hierarchical clustering revealed a group of proteins that have previously been reported to be expressed at elevated levels in ovarian cancer serum samples, including: CA125 (MUC16), HE4, MSLN, MK, KLK8, KLK11, NECT4, FOLR1, as well as KLK13, KLK14, and IL6." (PMID 35804849, 2022).
ovarian carcinoma (continued). "In light of the toxicity risk predicted above, and hoping to define a potential therapeutic window of FOLR1(Hi) TCB, we performed the same study with chips seeded with the high FOLR1 expressing ovarian carcinoma cell line, HeLa, previously used to assess drug efficacy." (PMID 34378534, 2021). "Activation of the Prot-FOLR1-TCB containing an MMP-matA site was observed for two undigested FOLR1 + ovarian carcinoma samples whereas no activation occured in a benign FOLR1 + ovarian sample." (PMID 32581215, 2020). "Ovarian cancer Phase I–III FIGS trials are being performed with untargeted dyes, such as indocyanine green (ICG) and contrast agents that target the folate receptor alpha (FRα)." (PMID 33260974, 2020). "Folate receptor alpha, mesothelin, MUC16, TROP2, tissue factor, and NaPi2b are common antigens used for conjugation in this malignancy, as they are usually overexpressed in epithelial ovarian cancer." (PMID 32784819, 2020). "Robust upregulation of early T-cell activation marker CD69 was detected by flow cytometry for all three FOLR1-targeting biAbs and both ovarian cancer cell lines when compared to the negative control." (PMID 31497024, 2019). "To explore their utility in the treatment of ovarian cancer, we built a set of asymmetric biAbs in IgG1-like format that bind CD3 on T cells with a conventional scFv arm and folate receptor 1 (FOLR1) on ovarian cancer cells with a conventional or a chemically programmed Fab arm." (PMID 31497024, 2019). "The most relevant differential genes in this network were FOLR1 and ST6GALNAC1, suggesting that these two genes may affect ovarian cancer." (PMID 30996686, 2019). "The expression level of folate receptor alpha (FRα) is located highly rate in ovarian cancer though it is remained absent in normal tissues." (PMID 29849110, 2018). "FOLR1 mRNA expression did not prove to predict clinical outcome in type II cancers, although strong FOLR1 expression generally denotes ovarian cancers with highly aggressive phenotype." (PMID 27485273, 2016). "Neither in the whole cohort of ovarian cancers nor in the analysed type I and type II cancers a significant correlation between the expression of FOLR1 and its specific promoter methylation was revealed." (PMID 27485273, 2016). "Differential gene expression analyses comparing epithelial ovarian cancer (EOC) to normal ovary tissue identified several potential tumor antigens, including folate receptor 1 (folate receptor alpha; FORL1) which is reported to be overexpressed, especially in serous adenocarcinomas." (PMID 23880844, 2013). "In addition to PAX8, COPA complemented with pan-cancer analysis prioritized eight other lineage-restricted outliers (CDH6, CLDN16, FGF18, FOLR1, SLC34A2, SOX17, SPON1, WNT7A) displaying largely confined gene expression in ovarian cancer cell lines and tumor specimens." (PMID 31050342, 2019). "The purpose of this analysis was to develop a population pharmacokinetic model for farletuzumab, a humanized immunoglobulin (Ig)G1 monoclonal antibody (mAb) to the folate receptor alpha, which is a receptor over-expressed in ovarian cancer, but largely absent from normal tissue." (PMID 22955257, 2012). "In addition, high affinity folate receptor (FOLR1), which maps to 11q13.3-13.5, is expressed at an elevated level on the surface of over 80% of nonmucinous epithelial ovarian cancers." (PMID 8094291, 1993). "We observed in this independent set of samples that FOLR1, ITGB3, ITGA5 and ACSL4 have higher expression for majority of the ovarian cancer cases compared to the non-ovarian cases." (PMID 37884576, 2023).
breast carcinoma (57 papers, 2009 to 2026). "We determined that FOLR1 expression was associated with the inhibitory effect of MORAb-202 in breast cancer cell lines; however the rate of FOLR1 internalization or linker degradation should be considered by multidirectional studies." (PMID 33535554, 2021). "In this study, the novel ADC MORAb-202, which comprises an anti-FOLR1 antibody and farletuzumab-linked eribulin, demonstrated a significant inhibition of proliferation in the FOLR1-expressing breast cancer cell lines." (PMID 33535554, 2021). "In our in vitro study, cell sensitivity to MORAb-202 was clearly associated with the expression of FOLR1 in breast cancer cell lines." (PMID 33535554, 2021). "Folate receptor alpha (FRα) plays a significant role in breast cancer, particularly in aggressive subtypes such as triple-negative breast cancer (TNBC), in which it is overexpressed in approximately 71% of the cases." (PMID 41596732, 2026). "Folate receptor alpha is expressed at low levels in normal tissues, but is elevated in aggressive breast cancer types and can be utilized for targeted nanoparticle delivery." (PMID 41596732, 2026). "Folate receptor alpha (FRα) has long been the focus of therapeutics development in oncology across several solid tumors, notably ovarian, lung, and subsets of breast cancers." (PMID 40045156, 2025). "FOLR1 in breast cancer cells facilitates cellular uptake of folate and can enhance tumor proliferation, making it a potential target for cancer therapy." (PMID 40707586, 2025). "Studies have shown that the positive expression rate of folate receptor alpha (FR-α) in breast cancer is relatively high." (PMID 40703550, 2025). "Folate Receptor-Alpha (FRα): Another promising target, especially in patients with refractory breast cancer." (PMID 40940995, 2025). "Folate receptor alpha (FRα) is another target for a therapeutic vaccine in patients with breast cancer." (PMID 36351947, 2022). "For example, an overexpression of folate receptor alpha (FRα) has been seen in some ovarian, lung and breast cancer cells; this can be exploited by functionalizing a drug carrier with folate, which binds specifically to FRα, for active drug targeting." (PMID 35213957, 2022). "FOLR1 expression, cell proliferation, bystander killing effects, and apoptosis were evaluated in seven breast cancer and nine NSCLC cell lines treated with MORAb-202." (PMID 33535554, 2021). "In this study, we tested the effect of MORAb-202, a novel anti-FOLR1 antibody–eribulin conjugate, in breast cancer and non-small cell lung-cancer (NSCLC) cell lines." (PMID 33535554, 2021). "In this study, we tested the effects of novel anti-FOLR1 antibody–eribulin conjugate MORAb-202 in breast cancer and non-small cell lung cancer (NSCLC) cell lines." (PMID 33535554, 2021). "The novel anti-FOLR1 antibody–eribulin conjugate MORAb-202 has potential antitumor effects in breast cancer." (PMID 33535554, 2021). "T47D cells, which are the breast cancer cells with the highest expression of FOLR1, exhibited a significant inhibition of cell proliferation and tumor growth, in vitro and in vivo, respectively." (PMID 33535554, 2021). "We characterized the effect of MORAb-202, which is a novel ADC that comprises the anti-FOLR1 antibody conjugated to eribulin via a cleavable linker, on breast cancer and NSCLC cell lines." (PMID 33535554, 2021). "Recent studies demonstrate that approximately 30% of breast cancers express folate receptor alpha (FRA) and suggest that as many as 70–80% of late-stage metastatic triple-negative breast cancer (TNBC) tumors express this receptor." (PMID 33738611, 2021). "FOLR1 is overexpressed in many solid, epithelial-derived tumors including ovarian, lung, and breast cancer, but is also expressed to a lower degree on normal epithelial cells as found in the lung and kidneys." (PMID 34378534, 2021).
breast carcinoma (continued). "While a high-affinity FOLR1-TCB (FOLR1(Hi) TCB) was efficacious in human breast cancer patient-derived xenograft models, severe on-target toxicity in the lung of cynomolgus monkey was observed." (PMID 34378534, 2021). "MORAb-202 was associated with inhibited cell proliferation, with specific selectivity toward FOLR1-expressing breast cancer cell lines." (PMID 33535554, 2021). "In summary, we have described the development of folic acid-conjugated Gd2O3:Eu3+ nanoparticles with low toxicity that can be used as a fluorescent probe for the detection of Folr1 breast cancer in vivo." (PMID 29566719, 2018). "In view of that, the surface of Gd2O3:Eu3+ was functionalized with folic acid to target Folr1, which is frequently over-expressed in breast cancers." (PMID 29566719, 2018). "T-47D human breast cancer cells showed a significantly higher expression of Folr1 when compared to kidney cells (293T) or other breast cancer cell lines (MCF-7 and MDA-MB-231) and prostate cancer cell line (PC-3)." (PMID 29566719, 2018). "Among the mouse breast cancer cell lines tested, PyMT-R221A had 338-times more Folr1 mRNA than 4T1 cells." (PMID 29482561, 2018). "To confirm that FOLR1 protein expression correlated with the mRNA trends observed across breast cancer subtypes, we used immunohistochemistry to screen TMAs for membrane FOLR1." (PMID 25816016, 2015). "A correlation has been shown between intense overexpression of FOLR1 in breast tumors and poor prognosis, yet there is limited examination of the distribution of FOLR1 across clinically relevant breast cancer subtypes." (PMID 25816016, 2015). "Our first objective was therefore to use mRNA-seq data to compose a detailed expression pattern of FOLR1 mRNA among breast cancer subtypes." (PMID 25816016, 2015). "We did observe a significant difference in median FOLR1 expression between patients age (≤60, P = 0.002) when analysis was performed across all breast cancer subtypes, but this significance was lost when analysis was limited to TNBC tumors." (PMID 25816016, 2015). "Our study reports that FOLR1 expression, as assessed by RNA-sequencing and immunohistochemistry, varies widely among subtypes of breast cancer." (PMID 25816016, 2015). "In general, the protein expression data for FOLR1 reflected that observed for the mRNA across the breast cancer subtypes." (PMID 25816016, 2015). "Prior to our work, studies investigating FOLR1 expression in breast cancer had been largely limited to semi-quantitative immunohistochemistry." (PMID 25816016, 2015). "We demonstrate that both FOLR1 mRNA and protein abundance varies widely among subtypes of breast cancer, with subpopulations of each subtype expressing high FOLR1." (PMID 25816016, 2015). "The elevated expression of Folr1 in mammary tumors detected by microarray analysis was confirmed by quantitative real-time RT-PCR." (PMID 19197353, 2009). "It was of interest that Folr1 expression level varied within K14-cre;ApcCKO/+ mammary tumors depending on histology, and the ones that had elevated expression were those predominantly composed of acinar histology." (PMID 19197353, 2009). "On the contrary, the FOLR1 mRNA levels were decreased in six cancers including breast cancer (BRCA), lung squamous cell carcinoma (LUSC), head and neck squamous cell carcinoma (HNSC), kidney chromophobe (KICH), acute myeloid leukemia (LAML), and skin cutaneous melanoma (SKCM)." (PMID 38396800, 2024). "The protein expression levels of FOLR1 varied in both breast cancer and NSCLC cell lines." (PMID 33535554, 2021). "Cell sensitivity to MORAb-202 is clearly associated with FOLR1 protein and mRNA expression levels in breast cancer cell lines but not in NSCLC cell lines." (PMID 33535554, 2021). "MORAb-202 sensitivity was clearly associated with protein and mRNA FOLR1 expression in breast cancer cell lines but not in NSCLC cell lines." (PMID 33535554, 2021). "MORAb-202 preferentially inhibited FOLR1-expressing breast cancer cell lines." (PMID 33535554, 2021).
breast carcinoma (continued). "As such, these studies suggest the regulation of FOLR1 expression may be complex, depending on the particular breast cancer subtype, and involve both alternative promoter utilization and estrogen–dependent regulation." (PMID 25816016, 2015). "To explore this further, we used RNA-seq data from multiple patient cohorts to analyze the distribution of FOLR1 mRNA across breast cancer subtypes comprised of estrogen receptor positive (ER+), human epidermal growth factor receptor positive (HER2+), and triple negative (TNBC) tumors." (PMID 25816016, 2015). "In particular, expression of FOLR1 (folate receptor alpha) is increased relative to normal tissue in many types of epithelial cancer, including non-mucinous ovarian, endometrial, non-small cell lung, colorectal, and breast cancers." (PMID 26230496, 2015). "Folate receptor α (FOLR1), a glycosylphosphatidylinositol-anchored membrane protein, is an attractive target of ADCs, as it is largely absent from normal tissues but is overexpressed in malignant tumors of epithelial origin, including ovarian, lung, and breast cancer." (PMID 33535554, 2021). "However, several studies in breast cancer suggest that FOLR1 may also represent an important therapeutic target in primary breast cancers." (PMID 25816016, 2015). "Our central objective was to examine FOLR1 expression patterns in clinically relevant molecular subtypes of breast cancer (ER+, HER2+, and TNBC) to identify whether there was differential expression, and to explore a potential mechanistic role of FOLR1 in breast cancer cells." (PMID 25816016, 2015). "In this study, various breast cancer cell lines and endometrial cells were used to analyze different expression levels of multiple target antigens (EGFR, FOLR1, HER2, EpCAM, NG2, ANK3 and CTNNB1) through flow cytometry and fluorescence microscopy." (PMID 40422194, 2025). "ELU001 targets folate receptor 1 (FOLR1), a receptor abundantly expressed in certain breast cancer subtypes, using C-Dot nanoparticles." (PMID 39063977, 2024). "As a previous study has shown that folate–miR-34a is selectively targeted to breast and lung cancers overexpressing FOLR1, we first confirmed the functionality of our folate–miR-34a using the MDA-MB-231 breast cancer cells as the experimental control." (PMID 38396800, 2024). "Many studies have looked at the HER family, mesothelin (Meso), folate receptor alpha (FR‐α), NKG2D ligands, c‐MET, and mucin 1 (Muc1) as potential targets for breast cancer in vitro and in animal models that will be discussed in the following sections." (PMID 35762299, 2022). "The breast cancer cell lines T47D, MDA-MB-361, HCC1954, and MDA-MB-231, and the NSCLC cell lines HCC827, HCC4006, NCI-H441, and ABC-1 showed particularly high FOLR1 expression levels." (PMID 33535554, 2021). "Folate receptor alpha (FRα) is known to be upregulated in a variety of cancers, including non-small cell lung cancer (NSCLC) and breast cancer." (PMID 26943581, 2016). "CAR T-cell therapy in breast cancer has shown early promise, particularly in HER2-positive breast cancer, with several clinical trials underway that target different antigens such as mesothelin, EGFR, and folate receptor-alpha." (PMID 40940995, 2025). "For the treatment of breast cancer, preclinical studies are ongoing to examine the effects of CAR-T cell therapy on various tumor specific antigens including mucin 1 (MUC1), HER2, Lewis Y, mesothelin, and folate receptor alpha (FR-α)." (PMID 36387071, 2022). "Folate receptor-alpha (FR-α) is upregulated in non-mucinous tumors of epithelial origins such as breast cancer; however, its overexpression is mostly detected in the TNBC subtype 61,62." (PMID 34729098, 2021). "Although largely absent from normal tissues, FOLR1 has been reported to be overexpressed specifically in malignant tumors of epithelial origin, including ovarian, lung, and breast cancer." (PMID 33535554, 2021).